SNHG7 (small nucleolar RNA host gene 7)
Diseases named in the same sentence as SNHG7 in open-access papers (continued):
Sharing a sentence is not in itself a finding about the gene and the disease.
cancer (continued). "In addition, metformin action on other types of cancers by regulating ten lncRNAs including AC006160.1, Loc100506691, lncRNA-AF085935, SNHG7, HULC, UCA1, H19, MALAT1, AFAP1-AS1, AC026904.1 is described." (PMID 36849958, 2023). "Also the up-regulated SNHG7 and BAALC-AS1 were top DELs interactors in the BDE-209 network, and both are involved in cancer progression, including HCC, promoting cell proliferation and suppressing apoptosis." (PMID 36430946, 2022). "We found four paired lncRNA-mRNA exhibiting a substantially high SCNA frequency in cancers, including lncRNA FGD5-AS1 and PRKAR2A (KIRC, 44.2% and 44.4%), lncRNA TUG1 and CDC7 (LUAD, 25.9% and 23.6%), lncRNA TUG1 and DSC2 (LUAD, 25.9% and 26.1%) and lncRNA SNHG7 and PNMA2 (LUAD, 25.4% and 31.1%)." (PMID 32846981, 2020). "Interestingly, the most upregulated gene in low UMIS tumor cells was the long non-coding RNA, SNHG7, which was 3.48-fold upregulated in low UMIS tumor cells (log2(fold change) = −1.80, FDR ~ 0) and has been previously reported as a positive regulator of CTNNB1 expression in several cancers 34–38." (PMID 38627362, 2024).
tumor (38 papers, 2018 to 2025). "Twenty-two articles were associated with the level of SNHG7 and tumor progression or metastasis." (PMID 34979987, 2022). "Since tumor metastasis and anti-apoptosis often accompany the development of drug resistance, we explored whether SNHG7 is associated with drug resistance." (PMID 35646635, 2022). "Additionally, increased SNHG7 expression was found to be associated with tumor stage and progression (III/IV vs. I/II: HR = 1.76, 95% CI: 1.57–1.98, p<0.001)." (PMID 34979987, 2022). "When SNHG7 was silenced, autophagy levels decreased, and chemotherapy sensitivity increased by about 2.5 times, highlighting the critical role of SNHG7 as a tumor-promoting factor." (PMID 40723840, 2025). "As a result, SNHG7 fosters a dual chemoresistance mechanism in tumor cells and their surrounding immune landscape." (PMID 41409273, 2025). "High SNHG7 levels correlate with adverse tumor characteristics such as size, lymphatic metastasis, distant metastasis, tumor stage, and OS." (PMID 39161590, 2024). "We subsequently examined SNHG7 expression in different stages of GC malignancy and revealed that elevated SNHG7 expression was associated with advanced clinical features, such as TNM stage and tumor grade." (PMID 37999596, 2023). "LncRNA small nucleolar RNA host gene 7 (SNHG7) is another tumor-related lncRNA that induces GBM tumorigenesis by sponging miR-5095." (PMID 38204968, 2023). "SNHG7 expression was significantly upregulated in the tumor group as compared with normal tissues (p < 0.001)." (PMID 35747807, 2022). "The low expression group of SNHG16, SNHG6, SNHG11, FAM222A-AS1, RHPN1-AS1, SNHG1, and SNHG7 was accompanied by more immune cell infiltration, further supporting that PANoptosis plays a crucial role in the tumor immune microenvironment." (PMID 35646635, 2022). "Taken together, these articles demonstrated that SNHG7 plays an important role in tumor development and progression." (PMID 34979987, 2022). "And previous experiments have fully proved that SNHG7 can also affect tumor cell apoptosis, invasion and migration in COAD." (PMID 35646635, 2022). "SNHG7 expression was not only significantly correlated with race (p < 0.05) and residual tumor (p < 0.05), but was also closely correlated with OS (p < 0.05) and DSS (p < 0.01)." (PMID 35747807, 2022). "repressed SNHG7, which resulted in reduced survival, growth and migration of tumour cells and cell cycle arrest; these findings confirmed that SNHG7 accelerates BCa progression." (PMID 33968736, 2021). "Researchers have revealed various mechanisms by which SNHG7 regulates tumour cell activities in PCa." (PMID 33968736, 2021). "Like oncogenic/tumor suppressor lncRNAs, SNHG7 is found to exert its tumorigenic functions through interaction with other biological substances." (PMID 35111760, 2021). "These include larger tumor size, more advanced clinical stage, poor histologic grade, deeper tumor invasion, and lymph node metastasis in accordance with high SNHG7 expression in the affected patients." (PMID 35111760, 2021). "SNHG7 upregulation, evaluated by RT-PCR, results in enhanced cell migration, invasion, tumor growth, and reduced apoptosis." (PMID 34885097, 2021). "Collectively, promoted tumor growth on SNHG7 overexpression and/or suppressed tumor proliferation on SNHG7 knockdown is reported in a body of studies." (PMID 35111760, 2021). "Likewise, tumor-derived exosomal lncRNA small nucleolar RNA host gene 7 (SNHG7) promotes docetaxel resistance in LUAD." (PMID 41409273, 2025). "Importantly, the regulatory effect of metformin on the SNHG7/miR-3127 ratio was confirmed in a xenograft model of OC, in which metformin prevented the promotion of tumor growth by SNHG7 overexpression." (PMID 38004379, 2023). "Notably, as observed in the H19/let-7 interaction, downregulation of SNHG7 releases miR-3127 (which acts as a tumor suppressor) from its sequestration, increasing its expression and bioavailability." (PMID 38004379, 2023).
tumor (continued). "High expression of SNHG7 enhances tumor resistance to irinotecan." (PMID 35646635, 2022). "We discovered a strong associated between SNHG7 expression and race, residual tumor, OS, and DSS of COAD patients, with SNHG7 expression appearing to be higher in patients with certain characteristics, such as specific race and with residual tumor." (PMID 35747807, 2022). "Furthermore, an elevated neovascularization rate following SNHG7 overexpression is consistent with tumor progression conditions." (PMID 35111760, 2021). "Additionally, low lncRNA SNHG7 expression also leads to reduced proliferation, the migration, and invasion of tumor cells." (PMID 34709112, 2021). "Since inhibition of miR-485-5p only partially reversed SNHG7 function, there might be other binding sites or pathways for SNHG7 to participate in tumor promotion." (PMID 34512753, 2021). "Accumulating studies indicate that SNHG7 might be a regulatory molecule in diverse human neoplasms, including urological tumours." (PMID 33968736, 2021). "Moreover, they indicated that the high expression of SNHG7 was positively correlated with increased tumor size and advanced TNM stage." (PMID 34714775, 2021). "SNHG7 also causes arrest in the G1/G0 phase of the cell cycle; regulates signaling pathways, such as Wnt/β-Catenin and AKT/mTOR pathways; and represses tumor suppressors, such as P15 and P16." (PMID 35111760, 2021). "Moreover, results of immunohistochemical analysis demonstrated that SNHG7 promoted cell proliferation in tumour tissues (Ki‐67), as well as increased expression of metastasis related protein (MMP‐9)." (PMID 31478234, 2019). "Furthermore, SNHG7 upregulation was correlated with tumor size, lymphatic metastasis, distant metastasis, and tumor stage of clinicopathologic parameters." (PMID 29970122, 2018). "In order to research whether SNHG7 caused CRC growth in vivo, we conducted a subcutaneous tumor formation experiment in nude mice." (PMID 29915311, 2018). "In addition, we noted that the degree of DNA methylation of the SNHG7 promoter was negatively correlated with tumor progression in GC patients and that there appeared to be a feedback regulatory relationship between the level of m6A methylation of SNHG7 and the level of DNA methylation." (PMID 37999596, 2023). "In addition, SNHG7 promotes tumor chemo-resistance in various tumors." (PMID 35646635, 2022). "A further meta-analysis of studies describing tumor characteristics was performed to determine whether the SNHG7 expression was related to the clinical- pathological parameters, including age, gender, TNM stage, lymph node metastases, distant metastasis, and tumor differentiation." (PMID 34714775, 2021). "Moreover, SNHG7 overexpression promoted tumor proliferation and inhibited cell apoptosis." (PMID 29915311, 2018). "Multivariate analysis indicated that SNHG7 expression (95% CI 1.035–5.268; P = 0.030), lymphatic metastasis (95% CI 0.869–4.012; P = 0.045), distant metastasis (95% CI 1.586–5.275; P = 0.011), and tumor stage (95% CI 1.301–6.684; P = 0.002) were independent predictors of the prognosis of CRC." (PMID 29970122, 2018). "Overexpression of SNHG7 suppresses miR-331-3p-mediated downregulation of cyclin D1 and inhibition of epithelial-mesenchymal transition (EMT), thereby accelerating tumor progression." (PMID 41234719, 2025). "For example, tumor-killing immune cells in the high expression group of SNHG16, SNHG6, SNHG11, FAM222A-AS1, RHPN1-AS1, SNHG1, and SNHG7 were significantly lower than those in the low." (PMID 35646635, 2022). "A large number of studies have reported that targeted inhibition of DANCR, SLCO4A1-AS1, Linc00337, SNHG7/20, NEAT1, MALAT1, ES1 or MALAT1 can reduce the degree of malignancy of tumours at the cellular level and even in animal models." (PMID 35907897, 2022).
tumor (continued). "SNHG3, RMRP, PCAT6, and LSINCT5 expression positively correlated with tumor size and TNM stage, while high expression of MAFG-AS1, SNHG7, and TMPO-AS1 was closely related to histological grade, tumor size, TNM stage, and clinical stage of BCa patients." (PMID 34611133, 2021). "Furthermore, in vivo assay revealed that silence of SNHG7 could inhibit tumour growth." (PMID 31478234, 2019). "We therefore selected EZH2 target genes with tumour‐suppressive functions (KLF2, RND1 or PTEN) that could be involved in the link between SNHG7 and OC progression." (PMID 32420685, 2020).
digestive system cancer (2 papers, 2021 to 2022). A primary or metastatic malignant neoplasm involving any part of the digestive system. "Subgroup analysis showed that high expression levels of SNHG7 were also significantly associated with unfavorable OS in digestive system cancer (HR = 2.31, 95% CI: 1.90–2.80, p <0.001) and non-digestive system cancer (HR = 2.67, 95% CI: 2.12–3.37, p <0.001)." (PMID 34979987, 2022). "Subgroup analysis showed that high expression levels of SNHG7 were also significantly associated with unfavorable OS in digestive system cancer patients (HR = 2.31, 95% CI: 1.90–2.80, p<0.001) and non-digestive system cancer patients (HR = 2.67, 95% CI: 2.12–3.37, p<0.001)." (PMID 34979987, 2022).
bacterial infection (1 paper, 2023). "Other predicted lncRNAs (SNHG3, SNHG7, NORAD, AC023509.1, AC016876.2 and AC021078.1) can also be good subjects for further experimental tests to determine their exact role in bacterial infection and inflammation." (PMID 37169818, 2023).
cardiovascular disease (1 paper, 2024). "It is known that, SNHG7 plays an important role in cardiovascular disease." (PMID 39014478, 2024).
SNHG7 also shares sentences with these, for which no sentence is quoted: COVID-19 (2 papers); Hypopharyngeal Cancer (2); malignant pleural mesothelioma (2); oral squamous cell carcinoma (2); paraganglioma (2); pheochromocytoma (2); adenoma (1); brain cancer (1); chromophobe renal cell carcinoma (1); colorectal tumor (1); diabetic retinopathy (1); diffuse large B-cell lymphoma (1); heart failure (1); hypertrophy (1); ischemia (1); Lung squamous cell carcinoma (1); lymphoid neoplasm (1); mesothelioma (1); Neonatal sepsis (1); osteosarcoma (1); premature ovarian failure (1); psoriasis (1); thymoma (1); trauma (1); uterine carcinosarcoma (1).